TNFRSF17 (TNF receptor superfamily member 17)
Diseases named in the same sentence as TNFRSF17 in open-access papers (continued):
Sharing a sentence is not in itself a finding about the gene and the disease.
eczema (1 paper, 2024). "In conclusion, methylation at the upstream sites at TNFRSF17 in the cord blood at birth is associated with food allergy and eczema early in childhood." (PMID 39085570, 2024). "Methylation at the upstream sites at TNFRSF17 at birth is an independent factor affecting the prevalence of food allergy and eczema." (PMID 39085570, 2024). "The results of our study indicate different pathways for sIgE sensitisation and food allergy/eczema in the first years of life, first with increased methylation at the upstream site of TNFRSF17 and the second with decreased." (PMID 39085570, 2024). "We revealed that DNA methylation of TNFRSF17 is changed at birth in children developing food allergy and/or eczema at 12–18 months of life, with lower methylation in the food allergy/eczema group." (PMID 39085570, 2024). "Children with food allergy and/or eczema presented lower methylation for TNFRSF17." (PMID 39085570, 2024). "The altered TNFRSF17 methylation pattern in the cord blood at both single cg04453550 and mean methylation at upstream of TNFRSF17 was observed in children who developed food allergy and/or eczema in early childhood." (PMID 39085570, 2024). "We have observed significant association for DNA methylation at TNFRSF17 and infant eczema and/or food allergy, but not atopic sensitisation." (PMID 39085570, 2024). "We also did not achieve significant results for the gene expression of TNFRSF17 for both food allergy/eczema diagnosis and children’s atopic sensitisation." (PMID 39085570, 2024).
endometrial cancer (1 paper, 2022). Primary or metastatic malignant neoplasm involving the endometrium (mucous membrane that lines the endometrial cavity). "Multiple types of mutations in TNFRSF17 have been shown in endometrial cancer, intestinal cancer, and skin cancer." (PMID 36251702, 2022).
food allergy (1 paper, 2024). Gastrointestinal disturbances, skin eruptions, or shock due to allergic reactions to allergens in food. "An association of TNFRSF17 with IgE-mediated food allergy has been revealed in study regarding infants." (PMID 39085570, 2024).
myocardial infarction (1 paper, 2024). Gross necrosis of the myocardium, as a result of interruption of the blood supply to the area, as in coronary thrombosis. "The IVW method revealed a significant association between TNFRSF17 and myocardial infarction risk, with an odds ratio (OR) of 0.9995 (95% CI = 0.9990–1.0000, p = 0.049)." (PMID 38977728, 2024). "The results of the MR study suggested a possible causative relationship between elevated myocardial infarct risk and serum TNFRSF17 levels." (PMID 38977728, 2024). "The inverse variance weighting analysis suggested an association between TNFRSF17 and myocardial infarction risk, with an odds ratio of 0.9995 (95% CI = 0.9990–1.0000, p = 0.049)." (PMID 38977728, 2024). "Our investigation centered on examining the causal effects of genetic variations on cardiovascular disease, with special attention to the relationship between TNFRSF17 levels and myocardial infarction." (PMID 38977728, 2024). "This evidence highlights the lack of a dominant SNP affecting TNFRSF17 levels and myocardial infarction, thereby affirming the credibility of our previous MR findings." (PMID 38977728, 2024).
seminoma (1 paper, 2024). A radiosensitive malignant germ cell tumor found in the testis (especially undescended), and extragonadal sites (anterior mediastinum and pineal gland). "In the tumor microenvironment of non-metastatic non-seminomas, TNFSF13B was highly expressed on FDC, cDC1 and cDC2 and promoted the proliferation through the receptors TNFRSF13B and TNFRSF17." (PMID 39528470, 2024).
thymoma (1 paper, 2022). A neoplasm arising from the epithelial cells of the thymus. "FAM46C expression was found to be positively correlated with TNFRSF17 and TNFRSF13B, except in DLBC, thymoma (THYM) and UCS." (PMID 35222533, 2022).
tumor (322 papers, 2009 to 2026). "Conversely, high tumor burden, elevated T-cell exhaustion markers, and genomic alterations such as heterozygous deletions of TNFRSF17 or GPRC5D at baseline have been associated with inferior outcomes." (PMID 40508128, 2025). "By scCNV-seq, the subclone with monoallelic loss of TNFRSF17 before anti-BCMA CAR T exposure accounted for 88.98% of the post-relapse tumor cells." (PMID 37653344, 2023). "Moreover, the strong correlation between CD79A and risk score, B cells, T cells, TIGIT, BTLA, CD27, and TNFRSF17 revealed the crucial role of CD79A in regulating the tumor microenvironment (TME) in LUAD patients." (PMID 35295857, 2022). "Additionally, the single nucleotide polymorphisms of TNFRSF17 can be associated with the tumour stage of CC." (PMID 36203424, 2022). "Consequently, we identified the TNFRSF17 gene as a core prognostic-associated gene for PCs, suggesting its potentially pivotal role in the underlying mechanisms contributing to the impact of tumor-infiltrating PCs in LUAD." (PMID 39619479, 2025). "By redirecting autologous or allogeneic T lymphocytes against tumor-associated antigens such as CD19 and TNFRSF17, CAR T-cells overcome resistance to conventional therapies." (PMID 41940327, 2026). "Tumor-intrinsic mechanisms contributing to secondary resistance include biallelic deletions or mutations affecting key target antigens, such as TNFRSF17 (BCMA) and GPRC5D." (PMID 40508128, 2025). "When TNFRSF17 was overexpressed, the proliferation and migration of CC cells were decreased, which indicates that TNFRSF17 plays a role as a tumour suppressor gene in the process of CC disease." (PMID 36203424, 2022). "Results revealed that high FAS, TNFRSF14, TNFRSF17, TNFRSF1B, and TNFSF13B expressions are associated with a high probability of “hot” tumor." (PMID 36588791, 2022). "On the other hand, the relationship between the overexpression of TNFRSF17 and its global contribution to/reflection of the tumor microenvironment requires further study." (PMID 36241983, 2022). "Among these, TNFRSF17 exhibited specific expression in tumor-infiltrating PCs." (PMID 39619479, 2025). "This discordance may be explained by the significant tumor burden (Metabolic Tumor Volume26 >240; beta 2 microglobulin= 9) in this second patient, and points to the presence of a residual reservoir of tumor cells with retained TNFRSF17." (PMID 41415462, 2025). "TNFRSF17 also has the potential to act as a marker for evaluating tumor immune infiltration status and it may predict beneficial effects of immune checkpoint blockade antigens." (PMID 36241983, 2022). "Moreover, our study suggests that TNFRSF17 may play a critical role in the potential mechanisms for PC's anti-tumor immunity." (PMID 39619479, 2025). "Oncogenes show specific activity in tumor cells, with LMO2, LYN, TNFRSF17, CARD11, and BCL7A being active in Tumor B1, while BCL2 and WAS are specifically active in Tumor B2." (PMID 41238550, 2025). "Based on above three diagnostic markers, we developed a diagnostic nomogram for TNBC patients, which showed that patients with high expressions of CD86, TNFRSF17, and TNFRSF1B had a high probability of “hot” tumor." (PMID 39007147, 2024). "In particular, based on high level of SDC1, TNFRSF17, MZB1, CD38 and low level of CD19 and MS4A1, Cluster 0, Cluster 1 and Cluster 12 were defined as SDC1+ cells, namely plasma cell in HD controls and tumor cells in MM patient." (PMID 36532059, 2022). "Patients with CC with high MS4A1 and TNFRSF17 expression had lower stemness scores, which further indicates that MS4A1 and TNFRSF17 can act as tumour suppressor genes." (PMID 36203424, 2022). "Also important are TNFRSF17, TNFRSF18, TNFRSF4, members of the Tumor Necrosis Factor Receptor superfamily that bind to various TRAF family members and can regulate tumor cell proliferation and death." (PMID 39888956, 2025).
tumor (continued). "Tumor samples with a positive HPV status expressed significantly higher levels of all of the B cell-related genes analyzed, namely, BLK, CD19, CR2, HLA-DOB, MS4A1 and TNFRSF17." (PMID 31623665, 2019). "A positive co-expression of ENHO with TNFRSF17, a B-cell maturation factor, suggests that ENHO may facilitate the recruitment of more mature B cells into the tumor microenvironment, thereby contributing to anti-tumor effects." (PMID 40647442, 2025). "Interestingly, we noted that WM-PC populations, sub-C7 (SDC1+TNFRSF17+) and sub-C11 (SDC1+CD3+), presented in low-tumor infiltration patients but were absent in high tumor infiltration ones." (PMID 36494694, 2022).
cancer (96 papers, 2015 to 2026). A tumor composed of atypical neoplastic, often pleomorphic cells that invade other tissues. "Additionally, in vitro experiments were conducted to examine the effects of MS4A1 and TNFRSF17 on cancer proliferation, migration, invasion and other phenotypes." (PMID 36203424, 2022). "In silico and data-mining analyses suggest that FAM171A1 has been predicted to interact with FAM171B, PCDHGB1, TNFRSF17, TMEM, CTDSPL, and NTRK1, many of which have been already implicated in various cancers suggesting most likely its possible role in the tumorigenesis." (PMID 30631046, 2019). "Other targets, including TNF receptor superfamily member 17 (TNFRSF17), CD22, CD38, CD33, and C-type lectin domain containing 14A (CLEC14A), demonstrated consistent but lower targeting potential across cancers." (PMID 39439803, 2024). "However, the biological role of TNFRSF17 in other cancers remains unclear include CC." (PMID 36203424, 2022). "The significant KEGG pathways are chemokine signaling pathway (CCL5, CCL18, CCL19, CCL21, CXCL12, CXCL14, CXCL13), ​​NF-kappa B signaling pathway (CCL19, CCL21, CXCL12), intestinal immune network for IgA production (TNFRSF17, CXCL12), pathways in cancer (IGF1, CXCL12)." (PMID 35486660, 2022).
hematological malignancies (68 papers, 2011 to 2025). "Targets of BsAbs developed for hematological malignancies, including CD19, CD20, CD33, CD38 (also known as ADPRC1), CD123, and B-cell maturation antigen (BCMA, also known as TNFRSF17), are commonly expressed on normal B and plasma cells." (PMID 40565299, 2025).
infection (18 papers, 2016 to 2026). The state of being infected such as from the introduction of a foreign agent such as serum, vaccine, antigenic substance or organism. "We validated this using smFISH, confirming that both Tnfsf13 and its cognate receptor Tnfrsf17 (encoding for the B cell maturation antigen, BCMA) are upregulated in microglia and B cells, respectively, upon infection." (PMID 36180478, 2022). "Analysis of cell-cell interactions between neutrophils and PCs showed that during infection, the latter downregulate key survival receptors such as BCMA (Tnfrsf17) and TACI (Tnfrsf13b)." (PMID 37669943, 2023).
blood cancer (13 papers, 2019 to 2025). "However, other blood tumor clinical CAR-T target genes, CD22 and TNFRSF17, are not essential in any cell line of their respective indications." (PMID 37835579, 2023).
immune diseases (4 papers, 2014 to 2025). "We thus presume that the upregulated DEGs such as Cav1, CD200R1, TNFRSF17 and CXCR3 and downregulated DEGs such as EIF1AY and DDX3Y in healthy female may be involved in gender predominance of some immune diseases." (PMID 24741625, 2014). "Moreover, the upregulated DEGs (Cav1, CD200R1, TNFRSF17, and CXCR3) and downregulated DEGs (EIF1AY and DDX3Y) in healthy female may be involved in gender predominance of some immune diseases." (PMID 24741625, 2014).
colon polyps (1 paper, 2022). "Patients with CC having a high expression of TNFRSF17 showed some differences in the M stage of CC and history of colon polyps." (PMID 36203424, 2022). "When TNFRSF17 expression was high, The proportion of distant metastasis was lower, but the proportion of history of colon polyps was higher." (PMID 36203424, 2022).
TNFRSF17 also shares sentences with these, for which no sentence is quoted: lymphoma (51 papers); B cell lymphoma (34); acute lymphoblastic leukemia (24); autoimmune disease (24); diffuse large B-cell lymphoma (19); non-Hodgkin lymphoma (18); acute myeloid leukemia (17); mantle cell lymphoma (17); hematological cancers (15); plasma cell dyscrasias (10); chronic lymphocytic leukemia (9); B-cell acute lymphoblastic leukemia (8); follicular lymphoma (8); Hodgkins lymphoma (8); myasthenia gravis (7); plasma cell leukemia (6); glioma (5); melanoma (5); neuroblastoma (5); rheumatoid arthritis (5); T-cell lymphoma (5); acute B-cell lymphocytic leukemia (4); Burkitt lymphoma (4); hepatocellular carcinoma (4); monoclonal gammopathy of undetermined significance (4); Parkinsonism (4); neutropenia (3); Obesity (3); POEMS syndrome (3); systemic sclerosis (3).
A further 99 diseases each share a sentence with TNFRSF17 in 3 papers or fewer.